RNU6-352P (RNA, U6 small nuclear 352, pseudogene)
Gene: Small nuclear RNA gene on chromosome 1 (101,859,851 to 101,859,957, forward strand). Ensembl gene ENSG00000252717.
Homologues: Orthologues: chimpanzee U6 (98% identical), macaque U6 (90% identical), dog U6 (63% identical), rat LOC120094870 (54% identical). Paralogues in human: RNU6-753P (71% identical), RNU6-1243P (70% identical), RNU6-331P (70% identical), RNU6-43P (70% identical), RNU6-1175P (69% identical), RNU6-11P (69% identical), RNU6-1311P (69% identical), RNU6-140P (69% identical), RNU6-312P (69% identical), RNU6-338P (69% identical), RNU6-34P (69% identical), RNU6-37P (69% identical), and 1288 more.